RNU7-175P (RNA, U7 small nuclear 175 pseudogene)
Gene: Small nuclear RNA gene on chromosome 5 (75,538,598 to 75,538,658, reverse strand). Ensembl gene ENSG00000251724.
Homologues: Orthologues: chimpanzee U7 (100% identical), macaque U7 (92% identical), pig U7 (75% identical). Paralogues in human: RNU7-167P (87% identical), RNU7-7P (87% identical), U7 (87% identical), RNU7-19P (85% identical), RNU7-105P (84% identical), RNU7-137P (84% identical), RNU7-143P (84% identical), RNU7-35P (84% identical), RNU7-67P (84% identical), U7 (84% identical), RNU7-11P (82% identical), RNU7-34P (82% identical), and 143 more.